USP14 (ubiquitin specific peptidase 14)
Diseases named in the same sentence as USP14 in open-access papers (continued):
Sharing a sentence is not in itself a finding about the gene and the disease.
ischemic stroke (4 papers, 2019 to 2023). A stroke disorder caused by obstruction of blood flow to the brain, due to thrombotic (local blood clot formation) or embolic (due to a blood clot or other material traveling from another site) event. "Taken together, these findings indicate that hsa_circ_0007706, derived from USP14, may be implicated in ischemic stroke." (PMID 34563140, 2021). "Identification of this novel role of USP14 has implications for research on the pathology of ischemic stroke as well as other CNS diseases." (PMID 37269080, 2023). "Recently, a study also showed that USP14 inhibition downregulated NCAO4 expression to prevent neuronal ferroptosis after ischemic stroke." (PMID 37269080, 2023). "In the present study, using a mouse model of middle cerebral artery occlusion (MCAO), we examined the effect of the USP14 inhibitor IU1 on BBB function after ischemic stroke in mice." (PMID 37269080, 2023). "For example, injection of the USP14‐specific inhibitor IU1 attenuates neuronal damage resulting from ischemic stroke by directly reducing abnormal protein aggregation." (PMID 37269080, 2023). "In this study, we demonstrated the anti‐inflammatory effect of the USP14 inhibitor IU1 after ischemic stroke." (PMID 37269080, 2023). "Given the central role of endothelial cells in regulating BBB structure, we attempted to clarify the role of USP14 in BBB dysfunction after ischemic stroke." (PMID 37269080, 2023). "Then, using NeuN to label neurons and CD31 to label endothelial cells, we found that USP14 was expressed on the neurons and endothelial cells after ischemic stroke." (PMID 37269080, 2023). "Ubiquitin-specific protease 14 (USP14), a direct downstream target of miR-124, has been shown to attenuate ischemic brain injury and promote neuronal survival in ischemic stroke." (PMID 33841091, 2021). "Exosomal miR-124 derived from M2 microglia has been found to be taken up by neurons and exert neuronal protective effects in ischemic stroke through attenuating neuronal apoptosis via downregulating Usp14." (PMID 31878035, 2019). "In this study, we tested the role of USP14 in disrupting BBB integrity after ischemic stroke." (PMID 37269080, 2023). "Our results showed that ischemic stroke induced higher USP14 expression on endothelial cells and that IU1 injection could efficaciously attenuate ischemic brain injury and enhance neurological function." (PMID 37269080, 2023). "Ischemic stroke induced higher endothelial deubiquitinating enzymes Usp14 expression in the brain." (PMID 37269080, 2023). "Based on these results, targeting USP14 may represent an effective approach to inhibit neuroinflammatory reactions after ischemic stroke." (PMID 37269080, 2023). "However, the role of USP14 in BBB dysfunction after ischemic stroke is unclear." (PMID 37269080, 2023). "The results showed that ischemic stroke induced higher USP14 expression in the brain and that IU1 injection downregulated USP14 expression 3 days after MCAO (p = 0.0039 and p = 0.0448)." (PMID 37269080, 2023). "Taken together, these results suggest that the USP14‐mediated protein degradation pathway may contribute to alterations in ZO‐1 levels and subsequent disruption of BBB integrity after ischemic stroke." (PMID 37269080, 2023). "Furthermore, we showed that USP14 inhibition preserved BBB integrity and subsequently inhibited neuroinflammation by maintaining the expression of the tight junction protein ZO‐1, suggesting that it is a promising treatment approach for ischemic stroke." (PMID 37269080, 2023). "In addition, miR-124 suppresses apoptosis in ischemic stroke via directly targeting and upregulating Bcl2, Bcl-xl, Usp14, JAK/STAT3, and PI3K/AKT/Nrf2 signaling pathways, while other researchers reported that miR-124 promotes neuronal apoptosis through inhibiting iASPP and Ku70 in ischemic stroke." (PMID 31878035, 2019).
lymph node metastasis (4 papers, 2017 to 2023). "Collectively, our findings revealed that elevated USP14 is associated with lymph node metastasis and poor prognosis in HNSCC patients." (PMID 37686660, 2023). "Regarding the clinical samples, IHC staining indicated that a high expression of USP14 was also associated with patients’ lymph node metastasis and tumor stage." (PMID 37686660, 2023). "In addition, the expression level of USP14 was associated with the clinical stage and lymph node metastasis of HNSCC patients." (PMID 37686660, 2023). "Intriguingly, it was found that patients with elevated USP14 levels exhibited greater tumor volume and an increased likelihood of lymph node metastasis and distant metastasis." (PMID 37917013, 2023).
Sepsis (4 papers, 2020 to 2025). Sepsis is defined as life-threatening organ dysfunction caused by a dysregulated host response to infection. "Inhibition of USP14 promotes autophagy in M1 macrophages, which reduces the severity of sepsis induced by cecal ligation and puncture." (PMID 38699234, 2024). "Our results suggested that S5 targeting USP14 to enhance autophagy provides a potential therapeutic solution for sepsis." (PMID 32820146, 2020). "Targeting USP14 by S5 to enhance autophagy presents a promising therapeutic approach for sepsis." (PMID 40867920, 2025). "Research has shown that targeting USP14 may serve as a potential strategy for treating sepsis." (PMID 40867920, 2025). "The levels of CLU, BCL2L1, USP14, PTPN1, OPA1, and CREB3 were elevated during sepsis and demonstrated a positive correlation with sepsis score." (PMID 40867920, 2025). "In the Severe vs. Control group, the genes associated with ER stress, including CLU (p = 0.01), BCL2L1 (p = 0.015), USP14 (p = 0.046), BFAR (p = 0.004), and OPA1 (p = 0.012), demonstrated a significant positive correlation with sepsis score." (PMID 40867920, 2025). "This study presents findings on several genes linked to ER stress, including CLU, BCL2L1, USP14, BFAR, and OPA1, which showed a positive correlation with sepsis score and a negative correlation with the combined activities of antioxidant enzymes." (PMID 40867920, 2025). "Furthermore, a positive correlation was observed between cAMP responsive element binding protein 3 like 2 (CREB3L2) and BCL2L1, as well as between the expressions of USP14 and YOD1 deubiquitinase (YOD1) in sepsis." (PMID 40867920, 2025). "The inhibition of USP14 enhances autophagy in M1-like macrophages and mitigates CLP-induced sepsis." (PMID 40867920, 2025). "Therefore, this study has demonstrated that typically inhibiting USP14 promotes autophagy in M1-like macrophages and alleviates CLP-induced sepsis." (PMID 32820146, 2020).
cervical cancer (3 papers, 2020 to 2023). A primary or metastatic malignant neoplasm involving the cervix. "Firstly, to determine the underlying effect of IU1 (a selective inhibitor of USP14) on the proliferation of cervical cancer cells, we used the CCK-8 assay." (PMID 33061808, 2020). "In conclusion, this work has provided a novel insight into the interaction between proteasome-associated DUB USP14 and MDM2 in cervical cancer cells." (PMID 33061808, 2020). "The intersection of LASSO and SVM-RFE analyses revealed eight hub genes in cervical cancer, which were RBBP4, SRM, GCH1, USP14, TRAIP, CBX4, VEZF1, and TOM1." (PMID 36999051, 2023). "Furthermore, USP14 selective inhibitor IU1 decreased MDM2 expression, inhibited growth, and triggered apoptosis in cervical cancer cells." (PMID 36999051, 2023). "Thus, the present studies support the notion that USP14/MDM2-mediated activation of the UPS and autophagy contributes to the antitumor effects of IU1 in cervical cancer cells through MDM2 degradation." (PMID 33061808, 2020). "Here we demonstrated that IU1, as a pharmacological deubiquitinating enzyme USP14 selective inhibitor, dramatically decreased MDM2 expression, accompanied by blocking G0/G1 to S phase transition, reducing cell growth and triggering cell apoptosis in cervical cancer cells." (PMID 33061808, 2020).
glioma (3 papers, 2023 to 2025). A benign or malignant brain and spinal cord tumor that arises from glial cells (astrocytes, oligodendrocytes, ependymal cells). "Analysis of USP14 expression in the TCGA or CGGA glioma dataset revealed that increased expression of USP14 correlated with glioma tumor progression, with MES compared with CL and PN GBM subtypes, and with decreased patient survival." (PMID 39990235, 2025). "In TCGA glioma samples, USP14 showed positive correlation with CD44 and ALDH1A3, and inverse correlation with PN markers, SOX2 and OLIG2." (PMID 39990235, 2025). "Employing the R2 genomics platform to query the 99 DUBs for their association with the GO category of Regulation of the ERAD pathway, we identified 3 DUB genes in this category as differentially expressed in the glioma dataset: USP14, USP19, and USP25." (PMID 37892185, 2023). "Nevertheless, the role of USP14 in glioma remains to be elucidated." (PMID 39990235, 2025). "Consistently, USP14 protein was highly expressed in GBM, compared with low-grade gliomas (LGG) tissues." (PMID 39990235, 2025). "To further elucidate the significance of MST4, USP14, and p-ALKBH5 in the biological behavior of GBM, we conducted an immunohistochemical (IHC) analysis of their expression profiles in 64 de-identified glioma patient samples." (PMID 39990235, 2025). "This list of genes includes three DUBs (USP14, USP19, USP25) shared with the list of differentially expressed ERAD genes in glioma." (PMID 37892185, 2023). "Additionally, the mRNA expression levels of MST4/STK26, USP14, and ALKBH5 were positively correlated with ALKBH5 target genes, including FANCD2, FANCI, MKI67, and RAD51 within the TCGA and CGGA glioma datasets." (PMID 39990235, 2025).
Hepatic steatosis (3 papers, 2023 to 2025). Steatosis is a term used to denote lipid accumulation within hepatocytes. "Hepatic USP14 overexpression exacerbated diet-induced hepatic steatosis, inflammation and fibrosis in mice, in contrast to the results of hepatic USP14 knockdown." (PMID 37633951, 2023). "To further investigate the rationale for the role of USP14 in promoting hepatic steatosis, we assessed the effect of USP14 on CYP2E1 both in vivo and in vitro." (PMID 37633951, 2023). "To further investigate the function of USP14 in hepatic steatosis, we performed adenoviral shRNA-mediated USP14 knockdown in HFD-treated C57BL/6 mice." (PMID 37633951, 2023). "Histological and qPCR analyses revealed that CYP2E1 inhibition alleviated hepatic steatosis, inflammation, and fibrosis in USP14-overexpressing mice." (PMID 37633951, 2023). "Previous research has demonstrated that hepatic USP14 expression is much higher in NAFLD patients and that hepatic USP14 overexpression exacerbates diet-induced hepatic steatosis, inflammation, and fibrosis in mice, in contrast to the results of hepatic USP14 knockdown." (PMID 40292292, 2025). "Thus, the function of USP14 in hepatic steatosis, especially the target of action of hepatic LPO, is not well studied." (PMID 37633951, 2023).
lymphoma (3 papers, 2012 to 2024). A malignant (clonal) proliferation of B- lymphocytes or T- lymphocytes which involves the lymph nodes, bone marrow and/or extranodal sites. "One way of targeting the proteasome is through USPs such as USP14 for different cancer types, including lymphoma, and even cancer cells resistant to bortezomib." (PMID 39664521, 2024). "Of particular interest was a band with the approximate molecular weight for USP14, a cellular DUB previously identified as a target of WP1130 in lymphoma cells (arrow head)." (PMID 22792064, 2012).
neuroblastoma (3 papers, 2015 to 2023). Neuroblastoma (NB) is the most common solid, extracranial childhood tumor. "Results demonstrated that an inhibitor of USP14 reduced PrPC in mouse neuroblastoma cells, as well as PrPSc, indicating that USP14 negatively regulates degradation of prion protein." (PMID 26061634, 2015). "USP14, HAUSP, and UCHL1 have been identified as key regulators of neuroblastoma differentiation and may play a critical role in neuroblastoma pathogenesis." (PMID 37170124, 2023).
Obesity (3 papers, 2018 to 2024). Accumulation of substantial excess body fat. "Glucose homeostasis is impaired in obesity, results in induced ER stress, and increases USP14 transcription level." (PMID 38673794, 2024). "Several USPs, including USP2, USP10, USP14, USP15, USP18, and USP22, have been associated with obesity and related metabolic disorders." (PMID 38322269, 2024). "The results above have shown that USP14 was upregulated in the obese livers, and overexpression of USP14 promoted obesity-induced hepatosteatosis." (PMID 30425250, 2018). "USP14 is also reported in regulating metabolic disease such as obesity and type 2 diabetes (T2DM)." (PMID 38673794, 2024). "Besides, human intestinal cell differentiation is altered during bariatric surgery, and USP14 can regulate human enterocyte differentiation and influence obesity." (PMID 38322269, 2024). "Thus, we propose that USP14 could be an important mediator for obesity-related hepatosteatosis." (PMID 30425250, 2018).
thyroid cancer (3 papers, 2023 to 2025). "To investigate the expression of USP14 in thyroid cancer cell lines, we employed immunoblotting revealing that the protein levels of USP14 was lower in ML1 thyroid cancer cells compared with primary thyroid cells." (PMID 37711852, 2023). "We observed here that the expression of USP14 is downregulated in the ML1 thyroid cancer cells compared with primary thyroid cells." (PMID 37711852, 2023). "Together this shows that USP14 is decreased in the thyroid cancer cells, likely due to a reduced gene expression." (PMID 37711852, 2023). "In addition, inhibition of USP14 in thyroid cancer cells using the compound IU1, augmented LC3B-lipidation, and the autophagy flux." (PMID 39916840, 2025). "However, little is so far known about the roles of USP14 in thyroid cancer cell growth and migration." (PMID 37711852, 2023). "Similarly, UCHL5 demonstrated a significant increase in positive staining, from 0% (0/11) in normal tissues to 75% (6/8) in PTC and 100% (5/5) in ATC samples, highlighting the notable upregulation of USP14 and UCHL5 in thyroid cancer compared to normal thyroid tissues." (PMID 40804247, 2025). "This was however not observed with FTC-133 cells indicating that the USP14 levels may vary between different thyroid cancer cells, which will require further investigations." (PMID 37711852, 2023). "In contrast to ML1 cells there was no significant reduction of USP14 levels in the FTC-133 cells, suggesting a cell specific regulation of USP14 levels in the two thyroid cancer cell lines." (PMID 37711852, 2023).
acute myeloid leukemia (2 papers, 2015 to 2020). Acute myeloid leukemia (AML) is a group of neoplasms arising from precursor cells committed to the myeloid cell-line differentiation. "Interestingly, b-AP15, a dual inhibitor of Usp14 and Uch37, was shown to prevent protein degradation and inhibit tumor progression in acute myeloid leukemia models." (PMID 32033280, 2020). "We have demonstrated that CuPT and auranofin are the novel metal inhibitors of UCHL5 and USP14 of the 19S proteasome by using several tumor models, including hematological malignancies, several solid tumor models and primary cells of the acute myeloid leukemia patients." (PMID 26097878, 2015).
aortic stenosis (2 papers, 2020 to 2025). Aortic valve stenosis is a aortic valve disease caused by the incomplete opening of the aortic valve. "Many algorithms and experimental methods have been used to identify and verify the USP14 as an underlying gene biomarker for aortic stenosis." (PMID 32471496, 2020). "Therefore, the consequence of Wnt/β-catenin activation, due to USP14 Dvl de-ubiquitination, is that cell proliferation would be activated greatly, which would cause aortic valve hypertrophy and then lead to aortic stenosis." (PMID 32471496, 2020). "There is a significant association between the high expression of USP14 and aortic stenosis, indicating that this gene may be a genetic risk factor for aortic stenosis." (PMID 32471496, 2020). "Western blotting revealed the expression levels of various proteins under different conditions (CON, aortic stenosis, aortic stenosis/USP14‐OE, aortic stenosis/USP14‐KO)." (PMID 40988122, 2025). "The immunohistochemistry assay manifested that USP14 was upregulated in the aortic stenosis tissues, compared with the control aortic valve." (PMID 32471496, 2020). "It is still necessary to further use an animal model to obtain more accurate results, in order to better understand the molecular mechanisms played by USP14 in aortic stenosis." (PMID 32471496, 2020). "Following verification of the patient samples, Ubiquitin-specific protease 14 (USP14) was found to be displayed at higher levels in the aortic stenosis samples." (PMID 32471496, 2020). "The RT-qPCR assay showed that the expression of USP14 was higher in the aortic stenosis than the control group (P < 0.05)." (PMID 32471496, 2020). "In this study, a WGCNA on microarray data from aortic valves predicted that USP14 would be highly expressed in the valves of aortic stenosis patients, which was effectively verified in molecular experiments with samples collected from patients." (PMID 32471496, 2020). "Moreover, in terms of the protein levels, the Western blotting confirmed that USP14 was up-regulated in the aortic stenosis tissue compared with the control group." (PMID 32471496, 2020). "DEGs, especially USP14, might be involved in the occurrence and development of aortic stenosis and might eventually become a biomarker and a target to treat this disease." (PMID 32471496, 2020). "USP14 may become a target for the diagnosis and treatment of aortic stenosis." (PMID 32471496, 2020). "USP14 might be involved in the occurrence and development of aortic stenosis, so it would be a molecular target for early diagnosis and specific treatment of aortic stenosis." (PMID 32471496, 2020). "This study found that USP14 is highly expressed in aortic valve tissue, which inhibits the proteasome degradation activity so this research hypothesizes that the inflammatory factors and lipoproteins gathered in the aortic valve cannot be effectively degraded, resulting in aortic stenosis." (PMID 32471496, 2020). "Knockdown and overexpression studies provided deeper insights into the mutual regulation mechanisms between USP14 and CDK4, suggesting that these proteins might synergistically influence the pathogenesis of aortic stenosis." (PMID 40988122, 2025).
bladder cancer (2 papers, 2021 to 2023). "Previous studies have demonstrated that USP21 and USP14 were upregulated in bladder carcinoma and played an important role in tumor cell proliferation and metastasis." (PMID 34769137, 2021). "Some studies have also found that USP14 and USP21 could function as oncogenes in bladder cancer." (PMID 34769137, 2021).
brain ischemia (2 papers, 2021 to 2023). Diminished or absent blood supply to the brain caused by obstruction (thrombosis or embolism) of an artery resulting in neurologic damage. "It has been suggested that miR-124 conferred a neuroprotective function by directly targeting USP14 after cerebral ischemia." (PMID 34563140, 2021).
brain tumor (2 papers, 2023 to 2025). "Our findings show that the USP14 inhibitor IU1 significantly increases the sensitivity of GSC-derived brain tumor xenografts to IR therapy, supporting the idea of targeting USP14 to enhance standard GBM treatment strategies." (PMID 39990235, 2025). "This study demonstrates that USP14 plays a role in the RNA m6A pathway and brain tumor biology by stabilizing ALKBH5." (PMID 39990235, 2025). "Inhibiting USP14 with the small molecule IU1 disrupts ALKBH5 deubiquitylation and increases the effectiveness of IR therapy on GSC-derived brain tumor xenografts." (PMID 39990235, 2025). "Although USP14 downregulation in several tumor types was shown to reduce tumor burden in mice, data are lacking for brain tumors." (PMID 37892185, 2023).